BRCA1 (BRCA1 DNA repair associated)
Diseases named in the same sentence as BRCA1 in open-access papers (continued):
Sharing a sentence is not in itself a finding about the gene and the disease.
invasive ductal carcinoma (continued). "patient: BRCA1 c.5266dupC het, p.Gln1756Profs*74 and BLM c.1642C>T het, p.Gln548Ter, which are known pathogenic variants; the patient was diagnosed with Grade 3 triple negative, invasive ductal carcinoma at the age of 32 years." (PMID 39148954, 2024). "The patient with the highest methylation at BRCA1, who developed a triple negative high-grade invasive ductal carcinoma at the age of 31 years, showed a mean blood methylation level of 0.25, possibly due to the presence of a constitutively hypermethylated allele." (PMID 30634417, 2019). "Invasive ductal carcinoma was the most prevalent type in both BRCA1 and BRCA2." (PMID 30820924, 2019). "Both these MBCs were from BRCA1/2 mutation negative patients with no family history of BC, were invasive ductal carcinomas, and presented with high grade (G3), ER-positive, HER2-negative and lymph node positive status." (PMID 27765917, 2016). "Siblings were eligible when index cases and at least one affected sister were diagnosed with infiltrating mammary or ductal adenocarcinoma, with no BRCA1/2 mutation." (PMID 26758370, 2016). "Invasive ductal carcinoma was the most common histological type in the two groups, but BRCA1 mutation non-carriers were more likely to have invasive lobular carcinomas." (PMID 24348864, 2014). "Our research investigated primary infiltrating ductal carcinoma cells, both with and without a BRCA1 gene mutation." (PMID 18366791, 2008). "Interestingly, our data also present a novel yet expected conclusion, which suggest that BRCA1-IRIS overexpression, which has been shown earlier to be associated with metastasis and poor survival in invasive ductal breast carcinoma is linked to uncoupling of the AKT-FOXO3a signaling axis." (PMID 25583261, 2015). "The majority of tumours were invasive ductal carcinoma in both BRCA2 (95.1 %) and BRCA1 (100 %) carriers." (PMID 26857456, 2016). "The patient was a 38-year-old premenopausal woman with TNBC (26 mm [measured by breast ultrasound] ER negative, PR negative, HER2 IHC 0, invasive ductal carcinoma, grade 3, in the right breast, lymph node-positive, BRCA1 positive, clinical N0)." (PMID 40045533, 2025). "While then number of patients with invasive ductal carcinoma was high in all three groups, a significantly higher proportion was observed in BRCA1/2 carriers (92.1%) and non-carriers (92.2%) compared to BRCA1/2 non-carriers (73.7%, p = 0.034)." (PMID 37791908, 2023). "We chose to focus our further studies on the SUM159 line due to its rapid growth rate and near-diploid genome with limited copy-number alterations, and its origin as an invasive ductal carcinoma, as compared with SUM149 which was derived from a BRCA1-mutant inflammatory breast cancer." (PMID 32393766, 2020). "Patient 3, exceeding the threshold by +0.10 at BRCA1, developed an invasive ductal carcinoma (estrogen and progesterone negative staining, HER2/neu positive staining, tumor size pT3, grade III, pN7/21) at the age of 28 years." (PMID 30634417, 2019). "The majority of TNBC and the non-TNBC groups tumors were histologically invasive ductal carcinomas (IDC) regardless of BRCA1-IRIS status." (PMID 28499366, 2017). "Patient P3 was diagnosed with stage II invasive ductal carcinoma at age 36 and does not have a copy of the BRCA1 gene." (PMID 25176351, 2014). "Invasive ductal carcinoma (no special type) was found to occur at the same frequency in both the BRCA1-positive group as well as the control group (87% and 85.8%, respectively)." (PMID 18405391, 2008). "For BRCA1 (D17S855, THRA1, D17S579) losses could be detected in invasive ductal carcinoma (IDC; n = 108) in 32-38%, invasive lobular carcinoma (ILC; n = 19) in 21-42% depending on the marker applied, but not in benign breast tumours (n = 15)." (PMID 8630282, 1996). "Most patients had invasive ductal carcinomas, regardless of whether they were BRCA1/2 carriers or not." (PMID 37485802, 2023).
peritoneal carcinoma (62 papers, 2007 to 2026). A peritoneum cancer that is located in the inside of the abdomen. "Here, we report a case of BRCA1 mutation-positive peritoneal carcinoma with cardiac tamponade due to malignant pericardial effusion that showed CR to platinum-based chemotherapy according to the RECIST criteria." (PMID 41209924, 2025). "Currently, BRCA1 and 2 mutation status testing is recommended for patients confirmed with ovarian, tubal, or peritoneal cancer." (PMID 37296748, 2023). "In carriers of a pathogenic BRCA1 mutation, the prevalence of ovarian, fallopian tube, and peritoneal cancers found during RRSO was 1.5% for those under 40 years old and 3.8% for those between 40 and 49 years old." (PMID 37519818, 2023). "This includes BRCA1/2-mutated metastatic pancreatic cancer in 2019, fallopian and primary peritoneal carcinoma in a combinational intervention with bevacizumab and HR-deficient metastatic castration-resistant prostate cancer in 2020." (PMID 36497275, 2022). "In this case, we reported a patient who first presented symptom of CRC and was finally diagnosed as BRCA1 associated HBOC with advanced peritoneal carcinoma." (PMID 36463302, 2022). "As previously reported, the prevalence of BRCA1/2 mutations in patients with peritoneal carcinoma or fallopian tube carcinoma is comparable to that in EOC patients." (PMID 32211327, 2020). "In this study, we determined the selected parameters such as age at cancer diagnosis, time from RRSO to the diagnosis of cancer, and significance of BRCA1 mutation type in patients diagnosed with breast or peritoneal cancer during postoperative follow-up." (PMID 30918533, 2019). "The carriers of c.181T > G and c.5266dupC BRCA1 mutation should be the subject further studies in context of breast and peritoneal cancer risk or time of cancer development after RRSO, respectively." (PMID 30918533, 2019). "We performed a statistical analysis of the frequency of peritoneal cancer in c.181T > G BRCA1 mutation carriers in comparison to other mutation carriers." (PMID 30918533, 2019). "Currently, the National Comprehensive Cancer Network guidelines recommend that all women with epithelial ovarian, fallopian tube, and primary peritoneal cancers be referred for genetic risk evaluation and be subjected to BRCA1/2 gene testing." (PMID 31064392, 2019). "One study showed an annual risk of peritoneal cancer after RRSO of 0.20% for women with BRCA1 and 0.10% for women with BRCA2, and in another study there was a 20-year cumulative risk of peritoneal cancer of 3.5%." (PMID 31888263, 2019). "Peritoneal cancers diagnosed during the follow-up period were observed only in two c.181T > G BRCA1 mutation carriers." (PMID 30918533, 2019). "The analysis included: age at cancer diagnosis, time from RRSO to the diagnosis of cancer, significance of BRCA1 mutation type in patients diagnosed with breast or peritoneal cancer during postoperative follow-up." (PMID 30918533, 2019). "JAMA Salpingo-oophorectomy and the risk of ovarian, fallopian tube and peritoneal cancers in women with a BRCA1 or BRCA2 mutation." (PMID 30636239, 2018). "Sitzmann and Wiebke point to several important facts in one of the most recent metaanalyses evaluating, among other things, the frequency of occurrence of peritoneal cancer after salpingo-oophorectomy in patients with BRCA1/BRCA2 mutation." (PMID 26928677, 2016). "The second, very important conclusion ensuing from this research is such that after prophylactic surgery peritoneal cancer develops more frequently in BRCA1 mutation carriers." (PMID 26928677, 2016). "Alsop and colleagues analyzed a series of 152 patients with peritoneal cancer and 40 with fallopian tube cancer and identified a total of 15.8% and 20% patients carrying a BRCA1/BRCA2 mutation, respectively." (PMID 27532258, 2016).
peritoneal carcinoma (continued). "The risk of primary peritoneal carcinoma is also increased in patients carrying BRCA1 (and BRCA2) mutations with a cumulative lifetime risk of between 1.3–20%." (PMID 17850658, 2007). "The United States Preventative Services Task Force currently recommends genetic counseling, and if indicated after counseling, genetic testing only for women with a personal or family history of breast, ovarian, tubal, or peritoneal cancer or an ancestry associated with the BRCA1/2 gene mutation." (PMID 36013212, 2022). "RRBSO <35/<45 years reduces the risk of ovarian/peritoneal cancer by 95% in BRCA1/2 PVCs and may be greater in specialist centres." (PMID 33152107, 2021). "Peritoneal cancer was only observed in two c.181T > G BRCA1 mutation carriers." (PMID 30918533, 2019). "BRCA1 protein loss is common in sporadic epithelial ovarian and peritoneal carcinomas." (PMID 19602291, 2009). "However, we found peritoneal cancer in two BRCA1 carriers with c.181T > G mutation, only." (PMID 30918533, 2019). "Subsequently, she was diagnosed with BRCA1-positive peritoneal carcinoma and was administered carboplatin, paclitaxel, and bevacizumab." (PMID 41209924, 2025). "Female patients with BRCA1 or BRCA2 mutations are at an increased risk of ovarian, fallopian tube, and peritoneal cancers." (PMID 38910622, 2024). "Expected annual rates of ovarian/peritoneal cancer were 1% for BRCA1 ≥ 35 years and 0.5% for BRCA2 ≥ 45 years." (PMID 33152107, 2021). "In response, provincial health ministries across Canada have expanded public health funding eligibility for BRCA1/2 testing to include all women with serous ovarian cancer, including FT and peritoneal cancer." (PMID 31061661, 2019). "Here, we evaluated the safety/tolerability, pharmacokinetics (PK), food effect, and efficacy of ABT-767 in patients with advanced solid tumors with BRCA1/2 mutations, and in patients with HGSOC, fallopian tube, or primary peritoneal cancer." (PMID 29313279, 2018). "Pathogenic germline BRCA1, BRCA2 (BRCA1/2), and several other gene variants predispose women to primary ovarian, fallopian tube, and peritoneal carcinoma (OC), although variant frequency and relevance information is scarce in Japanese women with OC." (PMID 29348823, 2017). "The rucaparib/carboplatin combination had radiologic antitumour activity, primarily in BRCA1- or BRCA2-mutated breast and ovarian/peritoneal cancers." (PMID 28222073, 2017). "Women that carry germ-line mutations for BRCA1 or BRCA2 genes are at an increased risk of developing breast, ovarian and peritoneal cancer." (PMID 17850658, 2007). "METHODS: Patients with genetically confirmed BRCA1/2 gPV diagnosed with ovarian, fallopian tube, or primary peritoneal cancer from May 1998 to April 2024 at our institution were included." (PMID 41692918, 2026). "In conclusion, to the best of our knowledge, this may be one of the first reported cases of an exceptional response to platinum-based chemotherapy in a patient with BRCA1-positive peritoneal carcinoma complicated by cardiac tamponade." (PMID 41209924, 2025). "Germline variants occurring in BRCA1 and BRCA2 give rise to hereditary breast and ovarian cancer (HBOC) syndrome, predisposing to breast, ovarian, fallopian tube, and peritoneal cancers marked by elevated incidences of genomic aberrations that correspond to poor prognoses." (PMID 38397209, 2024).
peritoneal carcinoma (continued). "For the primary disease site, the proportion of fallopian tube and peritoneal cancer was significantly higher in BRCA2+ (40.5%) compared with BRCA1+ (15.4%) and BRCA- (no pathogenic variant, 12.8%)." (PMID 33531027, 2021). "Preventative prophylactic bilateral salpingo-oophorectomy following the identification of a BRCA1 or BRCA2 gene mutation is associated with an 80% reduction in the risk of ovarian, fallopian tube (FT), or peritoneal cancer among BRCA1/2 carriers and a 77% reduction in all-cause mortality." (PMID 31061661, 2019). "A recent therapeutic breakthrough has been provided by PARP inhibitors for treatment or maintenance of BRCA1/2-mutated patients (about 15–20% of patients), and it is now approved for epithelial ovarian, fallopian tube and primary peritoneal cancer, as both treatment and maintenance." (PMID 34638503, 2021). "Another publication that may have confused the issue was an early report on fallopian tube and peritoneal cancers that suggested risks of only 0.6% and 1.3%, respectively, based on identification of BRCA1/2 in 5/29 (17.2%) and 9/22 (40%) of primary‐site tumours analysed." (PMID 33152107, 2021). "The six most commonly recurring BRCA1 and BRCA2 mutations previously identified in a founder French Canadian population were investigated in 439 histologically defined ovarian, fallopian tube and primary peritoneal cancer cases that were ascertained at one hospital servicing French Canadians." (PMID 25884701, 2015). "This was supported by a combined analysis of BRCA1 and BRCA2 in Kaplan‐Meier analysis with RRBSO having a HR for ovarian/peritoneal cancer of 0.029 (95% CI = 0.009‐0.100, P < .001)." (PMID 33152107, 2021). "BRCA1 and BRCA2 proteins are concordantly expressed in sporadic ovarian and peritoneal carcinomas." (PMID 19602291, 2009). "A similar positive rate of 7.4% (67/911) for non-BRCA genes has been recently reported in a cohort of 911 subjects selected on the basis of a personal history of breast and/or ovarian, fallopian, or primary peritoneal cancer, who were previously tested to be negative for BRCA1/2 genes." (PMID 29308099, 2018).
cervical cancer (61 papers, 2006 to 2026). A primary or metastatic malignant neoplasm involving the cervix. "Olaparib is a PARPi that was initially approved for the treatment of breast and cervical cancers with BRCA1 or BRCA2 functional deficiencies, inducing a synthetic lethality effect." (PMID 38270643, 2024). "Although we do not have substantial evidence that these recurrent BRCA1/2 variants are associated with cervical cancer and hepatocellular carcinoma, it still expanded the consideration of the potential role of BRCA1/2 for other cancer types." (PMID 32879886, 2020). "BRCA1 or 2 mutations were observed in 35%, 53%, and 38% of the sequenced tumors in ovarian, endometrial, and cervix cancers, respectively." (PMID 31771620, 2019). "One of these women with a prior history of cervical cancer diagnosed at 41 years of age was found to carry a BRCA1:C4446T mutation." (PMID 25884701, 2015). "Specifically, small molecules targeting the phospho-dependent interaction of BRCA1 with partners such as Abraxas were administered to breast and cervical cancer cells to mimic the inactivating mutation of the otherwise wild-type BRCA1 gene." (PMID 23781231, 2013). "Interestingly, that study proposed a significant association of pathogenic variants in BRCA1 or BRCA2 with cervical cancer (BRCA1: OR, 4.92; p = .01; BRCA2: OR, 4.46; p = .02) compared with an East Asian reference population in gnomAD." (PMID 39440754, 2025). "This early onset of cervical cancer in the context of a BRCA1 mutation may point to an increased risk in younger individuals with genetic predispositions." (PMID 40949480, 2025). "Somatic biallelic inactivation observed in some of these HRR variants and the moderate cervical cancer risk of BRCA1/2 P/LP variants further support that at least some of these germline findings may be driving events in cervical cancer." (PMID 37523182, 2023). "BRCA1/2 P/LP variants were also associated with moderate risks for endometrial and cervical cancer." (PMID 37523182, 2023). "Given the potential importance of BRCA1 loss as a predictive and prognostic biomarker in several cancers, the objective of this study was to investigate BRCA1 expression using immunohistochemistry (IHC) in cervical cancer and its possible prognostic relevance." (PMID 34820332, 2021). "BRCA1 expression in cervical cancer tissue is associated with survival." (PMID 34820332, 2021). "In current study, low BRCA1 expression was associated with inferior prognosis in cervical cancer." (PMID 34820332, 2021). "This study was initiated with hypothesis that BRCA1 expression may be associated to prognosis in cervical cancer." (PMID 34820332, 2021). "In addition, we identified genes associated with BRCA1 expression in cervical cancer to determine its clinical significance." (PMID 34820332, 2021). "In the present study, we corroborated the potential impacts of BRCA1/2 pathogenic variants or VUS in other cancers and detected two hepatocellular carcinoma patients carrying BRCA2 variants (c.7409dup and c.4307T>C) and one cervical cancer patient harboring BRCA1 c.4801A>T." (PMID 32879886, 2020). "However, the patient’s BRCA1 mutation could have further predisposed her to developing cervical cancer, a phenomenon observed in some studies that suggest women with BRCA mutations may have a higher risk of HPV-related malignancies." (PMID 40949480, 2025). "While HRD and pathogenic BRCA1/2 mutations are established predictive biomarkers for PARP inhibitor sensitivity in cancers such as ovarian and breast, their role in cervical cancer remains under investigation." (PMID 41008807, 2025). "Although the majority of cervical cancers are HPV-driven, this case underscores the potential synergistic effect of a BRCA1 mutation in facilitating the development of an HPV-associated malignancy." (PMID 40949480, 2025). "We also observe that BRCA1 is identified among the positive genes of both uterine and cervical cancer patients." (PMID 38976671, 2024).